SPRR2E (small proline rich protein 2E)
Description:
Cross-linked envelope protein of keratinocytes. It is a keratinocyte protein that first appears in the cell cytosol, but ultimately becomes cross-linked to membrane proteins by transglutaminase. All that results in the formation of an insoluble envelope beneath the plasma membrane.
Tractability: Antibody: its Gene Ontology location is reachable by antibodies, with high confidence.
Gene: Protein-coding gene on chromosome 1 (153,093,135 to 153,106,184, reverse strand). Ensembl gene ENSG00000203785.
Subcellular location: Cytoplasm
Pathways (Reactome):
Developmental Biology: Formation of the cornified envelope
Gene Ontology:
Molecular function: protein binding; structural constituent of skin epidermis; structural molecule activity
Biological process: cornification; epidermis development
Cellular component: cornified envelope; cytoplasm; cytosol
Genetic constraint (gnomAD): Loss-of-function variants: 1 observed, 2.33 expected, observed/expected ratio (o/e) 0.43, 90% interval 0.15 to 1.66. That is too few expected variants to judge how well the gene tolerates losing a copy. Missense variants: 68 observed, 78.49 expected, observed/expected ratio (o/e) 0.87, 90% interval 0.71 to 1.06. Synonymous variants: 20 observed, 26.96 expected, observed/expected ratio (o/e) 0.74, 90% interval 0.52 to 1.08.
Homologues: Orthologues: chimpanzee SPRR2E (100% identical). Paralogues in human: SPRR2B (97% identical), SPRR2D (97% identical).
Diseases named in the same sentence as SPRR2E in open-access papers:
SPRR2E is named in the same sentence as 6 diseases in open-access papers, as found by Europe PMC text mining. Sharing a sentence is not in itself a finding about the gene and the disease. The quoted sentences say what the papers report.
cancer (3 papers, 2018 to 2024). A tumor composed of atypical neoplastic, often pleomorphic cells that invade other tissues. "Within the family of small proline-rich proteins (SPRR), SPRR2B and other members like SPRR2E are of particular interest in oncology due to their roles in cancer progression." (PMID 39000413, 2024). "We found that there were no studies reporting association between SPRR2E and cancer, therefore, this gene needs to be further validated in a larger GBC cohort." (PMID 32547950, 2020). "Moreover, the approach has also emphasized the importance of the small proline-rich protein family (SPRR), including SPRR2B, SPRR2E, and SPRR2D, recognized for their significant involvement in cancer-related pathways and their potential as therapeutic targets." (PMID 39000413, 2024). "Additionally, the GLMQL-MAS system highlighted the small proline-rich protein family (SPRR) including SPRR2B, SPRR2E, and SPRR2D, noted for their significant roles in cancer-related pathways and their potential as therapeutic targets." (PMID 39000413, 2024). "Interestingly, cancer exosomes, but not normal exosomes, modulated expression of matrix remodelling (EFEMP1, DDK3, SPARC), cell cycle (EEF2K), membrane remodelling (LAMP2, SRPX), differentiation (SPRR2E), apoptosis (CTSC), transcription/translation (KLF6, PUS7)." (PMID 30008265, 2018).
tumor (3 papers, 2020 to 2025). "SPRR2E is the most significant up-regulated gene in tumor tissues (log2FoldChange = 30.54, adjusted P = 3.40E-09)." (PMID 32547950, 2020).
SPRR2E also shares sentences with these, for which no sentence is quoted: psoriasis (2 papers); cervical cancer (1); lung carcinoma (1); oral squamous cell carcinoma (1).